DDX60 (DExD/H-box helicase 60)
Diseases named in the same sentence as DDX60 in open-access papers (continued):
Sharing a sentence is not in itself a finding about the gene and the disease.
oral squamous cell carcinoma (3 papers, 2016 to 2022). "Herein, we evaluated the association of DDX60 expression with tumorigenesis and the prognosis of oral squamous cell carcinoma (OSCC)." (PMID 27835882, 2016).
lupus (2 papers, 2021 to 2025). "DDX60 is associated with serum activity in patients with systemic lupus erythematosus and may serve as a therapeutic biomarker." (PMID 39844327, 2025). "In addition, DDX60 has been reported to be associated with autoimmune diseases, such as systemic lupus erythematosus." (PMID 39844327, 2025).
pancreatic adenocarcinoma (2 papers, 2021). "DDX60 was revealed to be the most overexpressed RBP in pancreatic adenocarcinoma." (PMID 34912796, 2021).
tongue SCC (2 papers, 2016 to 2020). "Tongue squamous cell carcinoma (TSCC) or OSCC patients with high expression levels of DDX60, particularly those with moderately or poorly differentiated tumors, showed a poor disease-free survival (DFS)." (PMID 32765606, 2020). "DDX60 expression was examined by immunohistochemistry on tissue microarray slides of 494 OSCC patients, including 180 buccal mucosal SCC (BMSCC), 241 tongue SCC (TSCC), and 73 lip SCC (LSCC) patients." (PMID 27835882, 2016).
colitis (1 paper, 2017). Inflammation of the colon. "After induction of acute colitis with DSS, we found with EdgeR and CuffDiff2 analyses that the expression of 11 genes (Clps, Ddx60, Fgb, Fgg, Ifi44, Ifit2, Isg15, Itih3, Itih4, Oas3 and Usp18), which are involved in antimicrobial response, was increased in MMP-9−/− compared to WT mice." (PMID 28561062, 2017).
influenza infection (1 paper, 2015). "Broad compartmental expression of Ddx60 found here is the first suggestion that it may be systemically induced as an innate immune defense mechanism after influenza infection." (PMID 26413862, 2015).
leukemia (1 paper, 2023). A malignant (clonal) hematologic disorder, involving hematopoietic stem cells and characterized by the presence of primitive or atypical myeloid or lymphoid cells in the bone marrow and the blood. "Upon AOSD-NETs stimulation, the human leukemia monocytic cell line THP1 showed enhanced expression of IFI16 and DDX60 relative to HC-NETs, which was consistent with the expression pattern observed in AOSD patients." (PMID 38124139, 2023).
lip squamous cell carcinoma (1 paper, 2021). "A previous study has shown that high expression of DDX60 was significantly associated with poor survival in lip squamous cell carcinoma." (PMID 34178649, 2021).
lymph node metastasis (1 paper, 2025). "The mRNA expression level of DDX60 was correlated with lymph node metastasis and grade in clinical pancreatic patients." (PMID 39844327, 2025).
oral cancer (1 paper, 2016). "The clinical significance and biological function of DEXD/H box helicase 60 (DDX60) in oral cancer remains unknown." (PMID 27835882, 2016). "Moreover, oral cancer cells silenced using siRNA against DDX60 also showed reduced cell growth." (PMID 27835882, 2016). "Therefore, our data suggest that the effect of DDX60, a DEAD box protein, on tumorigenesis and the prognosis of oral cancer is subsite-specific, which is consistent with a previous study." (PMID 27835882, 2016). "Thus, DDX60 is a new independent negative prognostic biomarker of oral cancer, particularly for TSCC and LSCC." (PMID 27835882, 2016).
osteoporosis (1 paper, 2020). A condition of reduced bone mass, with decreased cortical thickness and a decrease in the number and size of the trabeculae of cancellous bone (but normal chemical composition), resulting in increased fracture incidence. "The gene that was not at the locus on chromosome 1 was DExD/H-box helicase 60 (DDX60) and is principally recognised as an RNA binding molecule with anti-viral properties, but it has also been mentioned as a potential candidate for osteoporosis in a study on human monocytes." (PMID 32093603, 2020).
squamous cell carcinoma (1 paper, 2018). A carcinoma arising from squamous epithelial cells. "For example, the DEXD/H box helicase 60 (DDX60) gene, a known regulator of the antiviral response and a DNA‐/RNA‐binding protein, has been reported to be associated with the development and prognosis of squamous cell carcinoma." (PMID 29193607, 2018).
ZIKV infection (1 paper, 2022). "Molecules involved in type I IFN signaling are also increased by ZIKV infection, such as STAT1, DDX60L, DDX60, DDX58, STAT2, and IRF7." (PMID 36142200, 2022).
infection (17 papers, 2015 to 2025). The state of being infected such as from the introduction of a foreign agent such as serum, vaccine, antigenic substance or organism. "Both Ddx60+/− and −/− mice had parallel weight loss curves following infection and titers of L. monocytogenes in the liver and the spleen, the primary sites of infection, were analogous in both groups." (PMID 26457795, 2015). "A set of upregulated in vitro and in vivo genes following infection were also strongly confined to Cluster 1 including Usp18, Tmem17 involved with tumor progression, and antiviral gene Ddx60." (PMID 40523037, 2025). "Later during infection, at 12 dpi, the top ten significantly upregulated genes with highest fold change included, similar to 4 dpi, Zbp1, Oas2, Gbp1, Ddx60, Oas1a and Mx1." (PMID 38536871, 2024). "In contrast, Ddx60-KO mice had increased mortality after infection with vesicular stomatitis virus and Ddx60 exhibited antiviral activity against hepatitis C virus (HCV)." (PMID 37963152, 2023). "CVA6 infection leads to the increased expression of ISGs, including Oas2, Irf7, Ddx60, Ifit3, Ddx58, and Isg15, which exhibit immunopathogenic potential and are implicated in neural inflammation." (PMID 36851724, 2023). "In the present study, two IFN-inducible cytoplasmic helicases were upregulated in chicken GIT post-infection: DDX60 (DExD/H-box helicase 60) and DHX58 (DExH-box helicase 58, also known as LGP2 (laboratory of genetics and physiology 2))." (PMID 34650121, 2021). "As expected, stimulation of MEFs with recombinant IFN (IFN‐A/D) or infection of BMMCs with SeV increased Ddx60 expression in Ddx60+/+ and Ddx60+/− cells." (PMID 26457795, 2015). "In contrast, Ddx60−/− mice behaved like Ddx60+/+ mice and lost weight as a result of the infection, but recovered within 11 days post infection (p.i.)." (PMID 26457795, 2015). "In sum, mouse DDX60 is dispensable for resistance to a wide range of experimental infections." (PMID 26457795, 2015). "Here, we used in vitro and in vivo approaches, including analysis of a Ddx60‐deficient mouse model, to find that murine DDX60 is dispensable for the induction of IFN‐α/β in response to different RLR agonists and for resistance to infection by multiple viruses." (PMID 26457795, 2015). "During E30 infection, genes associated with the type I IFN signaling pathway (Isg15, Mx1, Mx2, Sp100, Ifit1, Ifit3, Ifih1, Irf7, Irf9, guanylate-binding proteins 2 [Gbp2], and Stat1) and defense response to viruses (Ddx58, Ddx60, Zbp1, Oas2, Nlrc5, and Eif2ak2) were significantly upregulated." (PMID 36147849, 2022). "The 17 DEGs upregulated after infection with huH1N1 were shared with the swH1N1 infection (DDX58 (RIG-I), RSAD2 (Viperin), MX2, MX1, OAS1, ANGPTL4, IRF7, ISG15, IFIT1, ISG12(A), DDX60, BST2, IFI44, XAF1, LGALS3BP, RTP4, and IFI6)." (PMID 39247193, 2024). "We identified important genes DE in both our in vitro and in vivo infection models consistent with previous studies, namely, TLR3, IFIH1 (MDA5), SOCS1, OASL, DDX60, STAT1, MX1, CMPK2, LY96 (MD-2), STAT1, STAT2, TRIM25, IRF7, and IFIT5." (PMID 38675946, 2024). "We found that the type I interferon (IFN-I)-related genes, DDX60, IFI16, IRF7, ISG15, OAS1, and STAT1, were more highly expressed after Omicron breakthrough infection." (PMID 39835127, 2024). "Regulation of CXCR4, DDX60 and NFKBIZ varied at different time points after infection of chicken lungs." (PMID 32381003, 2020). "Likewise, the most abundant group of upregulated genes after infection with swH1N1 was ISGs or genes involved in their activation (DDX58 (RIG-I), ZBP1, IFIH1 (MDA5), IRF7, and DDX60)." (PMID 39247193, 2024). "For example, Ddx60-KO cells and mice showed no impairment in resistance to infection with various viruses, such as influenza A virus, encephalomyocarditis virus, Sindbis virus, vaccinia virus, or herpes simplex virus-1." (PMID 37963152, 2023).
infection (continued). "Three of these (lnc-DDX60-1 [ENSG00000248601,] lnc-THOC3-2 [ENSG00000248596)], and RP11-202G18.1 [ENSG00000227531] are transcripts of unknown function which may arise during transcription of neighboring genes related to cellular responses to infection and inflammation." (PMID 39395995, 2024).
cancer (11 papers, 2016 to 2024). A tumor composed of atypical neoplastic, often pleomorphic cells that invade other tissues. "Among them, the expression of AIM2/ASC/IL-18, MyD88, DAI, DHX36, and DDX60 were associated with cancer stages." (PMID 31949493, 2020). "From these studies, we speculated that DDX60 might be associated with other cancers." (PMID 32765606, 2020). "In addition, the expression of DDX60 in CRC was associated with cancer stages." (PMID 31949493, 2020). "The expression of DDX60 was upregulated in multiple cancers comparing with normal tissues, including GBM." (PMID 34178649, 2021). "Hence, the expression levels of DDX60 have certain relations with the occurrence, development, and prognosis of cancer." (PMID 32765606, 2020). "Previous studies showed that treatment with RIG-I agonist resulted in the activation of proinflammatory transcription factors STAT1 and NF-κB and increased expression of MHC-I components in cancer cells, Therefore, DDX60 may serve as a signaling transductor to activate the RIG-I pathway." (PMID 36551849, 2022). "Thus, DDX60 might also be involved in recurrence by regulating the EMT or cancer stem cell-like biomarkers in OSCC and TSCC, which should be further investigated." (PMID 27835882, 2016). "There have been reports that DDX60 was overexpressed in other types of cancers, but most of them did not further explore the intrinsic mechanisms." (PMID 34178649, 2021). "Key cancer-related transcripts were identified, such as CLDN1, TP63, FGF14, DDX60 and DRAM." (PMID 32839509, 2020). "Recent studies suggest that DNA sensors such as AIM2, TLR9, DHX9, DHX36 and adaptor STING may have roles in CRC development, and the other DNA sensors such as DDX41, DDX60, IFI16, and DAI participate in the development of other types of cancers." (PMID 31949493, 2020). "Moreover, DDX60 is a member of the DEAD box RNA helicase protein family, which is involved in most cellular processes essential for cancer development, such as cell proliferation." (PMID 27835882, 2016). "Interestingly, our results showed that the increased expression of DDX60 was correlated with well-differentiated TSCC and OSCC, which seems illogical in cancer." (PMID 27835882, 2016). "In addition, DDX60 might be able to sense the abnormal cytosolic RNA (viral, bacterial, or self-RNA) and activate MHC-I signaling in cancer cells." (PMID 36551849, 2022).
tumor (11 papers, 2015 to 2025). "Among OSCC patients, higher levels of DDX60 expression were associated with the male gender, a well-differentiated tumor, advanced stage of disease, and a large tumor size with subsite specific features." (PMID 27835882, 2016). "DDX60 has been shown to be associated with a variety of tumor biological processes." (PMID 39844327, 2025). "The results showed that DDX60 expression is significantly associated with tumor development in TSCC patients with BQ chewing (p<0.001), smoking (p<0.001), or alcohol drinking (p<0.001) compared to the expression in TSCC patients without BQ chewing, cigarette smoking, or alcohol drinking." (PMID 27835882, 2016). "We know that DDX60 is mainly involved in tumor-related pathways, immune-related pathways and drug metabolism-related pathways." (PMID 39844327, 2025). "By analyzing single cell sequencing data, we found that DDX60 was positively correlated with malignant tumor cells." (PMID 39844327, 2025). "ROC curve analysis showed that CXCL8, DDX60, IFI44l, RSAD2, and RTP44 had better diagnostic efficiency for normal and tumor tissues, and the combined diagnosis was more effective." (PMID 34384424, 2021). "At 48 h after irradiation, the expression of Ddx60 and p204 was maintained while additionally Dai mRNA became upregulated at the highest dose in tumor cells." (PMID 33202881, 2020). "In our study, among several tested DNA sensors, only Ddx60, Dai, and p204 were significantly upregulated in tumor cells after irradiation." (PMID 33202881, 2020). "For patients with high expression levels of DDX60, the new tumor event rate of the radiotherapy group was significantly higher than that of the nonradiotherapy group." (PMID 32765606, 2020). "Distinct DNA sensors were upregulated, with the most prominent being Ddx60, Dai and p204 in tumor cells and Ddx60, Dai, p204, and Rig-I in macrophages." (PMID 33202881, 2020). "The immunoreactivity of DDX60 was higher in tumor tissues compared to that in CTAN tissues at the buccal mucosa, tongue, and lip subsites." (PMID 27835882, 2016). "DDX60 expression was significantly increased in all three subsites of OSCC compared to its expression in tumor adjacent normal tissues." (PMID 27835882, 2016). "From this analysis, the following genes were identified: NAA11, HERC5, DDX60, and HERC6 which were evaluated individually for association with tumor recurrence using the 21 Chinese patient primary tumors." (PMID 26653219, 2015). "In addition, DDX60 was positively correlated with the immune score in the tumor immune microenvironment." (PMID 39844327, 2025). "Furthermore, DDX60 expression in CTAN (p<0.001) or tumor tissues (p= 0.049) was significantly different between the buccal mucosa, tongue, and lip subsites." (PMID 27835882, 2016). "Consistently, DDX60 expression was increased in tumor tissues and positively associated with larger tumor sizes in OSCC patients, particularly for TSCC and BMSCC, indicating that DDX60 might induce cell proliferation through the verified mechanisms of DDX proteins in tumorigenesis." (PMID 27835882, 2016). "When comparing the HPSCC cell lines FaDu and 2A3 in vitro, differences were observed in the expression levels of DDX60 and RIG-I, while in vivo models differed in cGAS and DAI expression in tumor cells." (PMID 41401057, 2025). "Our analysis showed that elevated DDX60 expression correlates with reduced relapse-free survival (RFS) and overall survival (OS), and it is particularly upregulated in more advanced tumor stages (N1) and in regions with higher malignancy." (PMID 39844327, 2025). "The Human Protein Atlas database showed that the protein expressions of DDX60, IFI44L, RSAD2, and RTP44 in tumor tissues were higher than those in normal tissues." (PMID 34384424, 2021).
tumor (continued). "This accumulation activated several distinct DNA sensing pathways, most prominently activated DNA sensors being DDX60, DAI, and p204 in tumor cells and DDX60, DAI, p204, and RIG-I in macrophages as determined by PCR and immunofluorescence imaging studies." (PMID 33202881, 2020). "Overall, a higher DDX60 expression was observed in OSCC patients with male gender (p= 0.002), low-grade cell differentiation (p= 0.004), advanced pathological stage (p= 0.023), and large tumor size (T3-T4, p= 0.001)." (PMID 27835882, 2016). "Furthermore, the ROC curve analysis showed that hub gene (CXCL8, DDX60, IFI44L, RSAD2, and RTP4) could distinguish OC from normal tissues, and the diagnosis effect of tumor tissue was better, and the combined diagnosis of five genes was the best." (PMID 34384424, 2021). "Our preliminary next generation sequencing and real-time PCR data indicated that DDX60 gene expression was increased in OSCC tissues compared to that of the corresponding tumor adjacent normal tissues (CTAN) (data not shown), suggesting that DDX60 may be involved in the tumorigenesis of OSCC." (PMID 27835882, 2016).
bacterial infection (1 paper, 2022). "Similar study supported a model in which m6A modifications in the Traf6 transcript regulated the intestinal immune response to bacterial infection via a complex consisting of YTHDF1, DDX60, and the Traf6 transcript." (PMID 36578521, 2022).
DDX60 also shares sentences with these, for which no sentence is quoted: atherosclerosis (1 paper); autoimmune disease (1); cardiac hypertrophy (1); fibrosarcoma (1); Glioma Malignancy (1); H1N1 virus infection (1); mesothelioma (1); pneumonia (1); pulmonary fibrosis (1); sarcoma (1); tauopathy (1).